SMAD7 (SMAD family member 7)
Diseases named in the same sentence as SMAD7 in open-access papers (continued):
Sharing a sentence is not in itself a finding about the gene and the disease.
Myocardial fibrosis (30 papers, 2016 to 2026). "On the other hand, few studies demonstrated the evidence that found an underlying correlation between decreased Smad7 and skin lesions, in a murine model of scleroderma and myocardial fibrosis in infracted heart." (PMID 26997760, 2016). "We previously reported that the high expression of TGF-β1 in pathological conditions could cause the down-regulation of Smad7, which contributes to the development of myocardial fibrosis in AF." (PMID 26968995, 2016). "Collectively, our findings reveal BMAL1 as a critical negative regulator of post-MI myocardial fibrosis by inhibiting the TGF-β1/SMAD3 pathway mediated by SMAD7." (PMID 41909150, 2026). "Downregulation of miR-195-5p inhibits endothelial-mesenchymal transition and myocardial fibrosis in diabetic cardiomyopathy by targeting Smad7 and the TGF-β1/Smads/Snail pathway." (PMID 41295241, 2025). "CircMACF1 alleviates myocardial fibrosis after acute myocardial infarction through miR-16-5p/SMAD7 signaling pathway as a novel target for AMI treatment." (PMID 40835966, 2025). "Studies have identified the increased expression of Smad7 in CFs as a critical strategy for improving myocardial fibrosis in DCM." (PMID 38072948, 2023). "This study revealed that Sal B can improve myocardial fibrosis in DCM by deubiquitinating Smad7, stabilizing the protein expression of Smad7, and blocking the TGF-β1 signaling pathway." (PMID 38072948, 2023). "Smad7 activation acts as a TGF-β-induced endogenous inhibitory signal that prevent myocardial fibrosis." (PMID 36878974, 2023). "According to previous reports, myocardial fibrosis promotes the ubiquitination of Smad7 and reduces its stability, which results in decreased expression of Smad7." (PMID 38072948, 2023). "Substantial evidence has shown that downregulating the expression of Smad7, myocardial fibrosis significantly deteriorate." (PMID 38072948, 2023). "It is imperative to recognize a noteworthy constraint: the examination of the mechanism by which Sal B improves myocardial fibrosis in this study has exclusively focused on animal and cellular levels, specifically involving Smad7." (PMID 38072948, 2023). "Myocardial fibrosis is associated with up-regulation of TGF-β1 and the downstream Smad2 and Smad3 proteins, as well as down-regulation of Smad7 expression." (PMID 35279096, 2022). "Collectively, silencing miR-195-5p inhibits TGF-β1-smads-snail pathway by targeting Smad7, thus inhibiting EndMT and alleviating myocardial fibrosis in DCM." (PMID 34658906, 2021). "In order to study the role of Smad7 in myocardial fibrosis, we transfected pcDNA3.1 or pcDNA3.1-Smad7 into LPS-stimulated H9C2 cells, the expression level of Smad7 in the pcDNA3.1-Smad7 group was higher than that in the pcDNA3.1 group." (PMID 35036160, 2021). "(2020) in a mouse hypertensive heart disease model showed that increasing Smad7 is expected to block Smad3-mediated myocardial fibrosis." (PMID 35036160, 2021). "MiR-21 can inhibit apoptosis and inflammation by targeting KBTBD7, regulate angiogenesis through STRN/NOS3, and promote myocardial fibrosis through the TGF-β/Smad7 signaling pathway." (PMID 35111829, 2021). "Studies have shown that in other pathological conditions, such as myocardial fibrosis in AF, which is attributed to the neurohumoral activation effect, the level of Smad7 is down-regulated." (PMID 35036160, 2021). "After AMI, miR-21 induces myocardial fibrosis through the TGF-0205/Smad7 pathway, and circRNA-010567 promotes myocardial fibrosis by inhibiting miR-141 via targeting TGF-β1." (PMID 32148552, 2020). "The animal test results indicated that Sal B significantly improved cardiac function, inhibited collagen deposition and phenotypic transformation, and ameliorated myocardial fibrosis in DCM by upregulating Smad7, thereby inhibiting the TGF-β1 signaling pathway." (PMID 38072948, 2023). "We confirmed that Sal B could prevent the ubiquitination of Smad7 to improve myocardial fibrosis in DCM." (PMID 38072948, 2023).
Myocardial fibrosis (continued). "In myocardial fibrosis after ischemia, circHNRNPH1 competitively binds to miR-216-5p, induces the expression of Smad7 to accelerate the degradation of TGF-β1, inhibits the migration of myofibroblasts and the expression of α-SMA and col-I, and alleviates the progression of myocardial fibrosis." (PMID 36675315, 2023). "Myofibroblast-specific Smad7 loss does not affect scar size, but is associated with expansion of myocardial fibrosis in the infarct border zone." (PMID 34905511, 2022). "In addition, fluvastatin can inhibit TGF-β1 and induce Smad7 expression in a dose-dependent manner, thereby delaying myocardial hypertrophy and myocardial fibrosis in spontaneously hypertensive rats." (PMID 34221074, 2021). "However, the regulation mechanism linking miR-21 and Smad7 in RAP-induced myocardial fibrosis was unclear." (PMID 26968995, 2016). "This study further confirmed our previous research that the down-regulation of Smad7 may be responsible for RAP-induced myocardial fibrosis." (PMID 26968995, 2016). "In the present study, our aim was to determine if miR-21 up-regulation could enhance TGF-β1-induced myocardial fibrosis by inhibiting Smad7." (PMID 26968995, 2016). "Therefore, we chose to study whether miR-15a-5p and Smad7 were involved in myocardial fibrosis by affecting the TGF-β1/collagen I pathway." (PMID 35036160, 2021). "Thus, the cardioprotection of SFI treatment in CHF for myocardial fibrosis may be achieved by upregulation of Smad7 and downregulation of TGF-β1, Smad2, and Smad3 gene expression via TGF-β/Smads signaling pathway." (PMID 28698735, 2017). "Thus, we speculate that miR-21 over-expression significantly enhances TGF-β1-induced collagen expression and that Smad7 can directly inhibit collagen expression in RAP-induced myocardial fibrosis." (PMID 26968995, 2016). "QL:reducte in myocardial fibrosis, promote TGF-β3/Smad7, and inhibite TGF-β1/Smad3;reverse Bax/Bcl-2 upregulation;inhibite Smad3 by upregulating miR-345-3p." (PMID 40881586, 2025). "Overall, besides of positive regulation to myocardial fibrosis by increased expression of SMAD2 and SMAD3, decreased expression of SMAD7 was closely related to collagen deposition, which negatively expedited fibrotic responses in patients with HOCM." (PMID 36878974, 2023). "It has been reported that simvastatin improved myocardial fibrosis in rats with MI by down-regulating TGF-β1 and downstream SMAD3 expression and up-regulating SMAD7 expression." (PMID 35498008, 2022). "Smad7 is involved in the regulation of TGF-β1, which is one of the important regulatory mechanisms of myocardial fibrosis in AF." (PMID 35036160, 2021). "In the KKAy mouse model with myocardial fibrosis, we found the overexpression of collagens I and III and α-SMA, as well as the activation of TGF-β1 and p-Smad2/3 and the reduction of Smad7." (PMID 34938743, 2021). "Overall, hyperglycaemia up‐regulated miR‐21, followed by down‐regulation of its target SMAD7, which, in turn, enhanced the phosphorylation of SMAD2 and SMAD3, thereby promoting EndMT activation and myocardial fibrosis." (PMID 31680453, 2020). "Discussion and Conclusions: The beneficial effects of QL on DOX-induced CHF in rats are mediated by reduction in myocardial fibrosis, promotion of TGF-β3/Smad7, and inhibition of TGF-β1/Smad3." (PMID 32429724, 2020). "In conclusion, we speculate that Smad7 may have mediated the interaction between TGF-β/Smad2/3 and Wnt/β-catenin in the TSF treatment of myocardial fibrosis." (PMID 34938743, 2021). "Previously, we have showed that GXD ameliorated heart injury and protected rats from myocardial fibrosis, which may be related to inhibiting the TGF-β1 signaling pathway by down-regulating expressions of Smad2/3 whereas improving Smad7 expression." (PMID 26846090, 2016). "However, there is no research to determine whether miR-15a-5p and Smad7 are related to the pathogenesis of myocardial fibrosis in AF." (PMID 35036160, 2021).
gastric cancer (27 papers, 2008 to 2025). A primary or metastatic malignant neoplasm involving the stomach. "On the other hand, SMAD3, SMAD5, SMAD6, and SMAD7 were associated with poor OS in the second and third stage of gastric cancer." (PMID 34138687, 2021). "In addition, SMAD6 and SMAD7 were associated with poor OS in poorly differentiated gastric cancer." (PMID 34138687, 2021). "The relationship between the expression of SMAD7 and lymphatic metastasis in gastric cancer has been reported." (PMID 35449091, 2022). "Analysis showed that high expression levels of SMAD1, SMAD2, and SMAD4 are associated with a better survival rate of gastric cancer patients, whereas SMAD3, SMAD5, SMAD6, SMAD7 and SMAD9 are associated with poor prognosis." (PMID 34138687, 2021). "For example, the expression of SMAD4 was lower, and that of SMAD7 was significantly higher, in the gastric cancer tissues than in the peri-tumoral tissues." (PMID 25295107, 2014). "Consistent with this is the demonstration that ectopic Smad7 expression increases the survival of SGC7901 gastric cancer cells." (PMID 24317436, 2013). "This group showed also up-regulation of Smad7 in gastric cancer and peri-tumoral area, particularly in poorly differentiated tumors and in those with lymphatic metastasis." (PMID 24317436, 2013). "It has been also reported that gastric cancer patients with elevated levels of Smad7 had a poor prognosis independently of other well-established clinical prognostic factors, such as tumor size, depth of invasion and lymph node metastasis." (PMID 24317436, 2013). "The expression of Smad7 in gastric cancer progression and its prognostic significance was initially investigated by Kim and colleagues." (PMID 24317436, 2013). "In agreement with our results, patients with colon and gastric cancers, with Smad7 gene deletion or low Smad7 protein expression, were described as having prolonged survival as compared to patients with higher Smad7 expression." (PMID 20462450, 2010). "In addition, SMAD7 sensitizes breast and gastric cancer cells to TNF-induced apoptosis through down-regulation of the NFκB signaling pathway." (PMID 35917315, 2022). "Similarly, the expression of SMAD4 was lower, whereas SMAD7 was found to positively correlate with tumor grading in human glioma and gastric cancer." (PMID 25295107, 2014). "Moreover, miR-106b functions in a similar way by targeting SMAD7 in gastric cancer." (PMID 33498521, 2021). "In addition, another miRNA originated from GC cells derived exosomes, miR-21-5p, could induce mesothelial-to-mesenchymal transition of peritoneal mesothelial cells and promote gastric cancer peritoneal dissemination by targeting SMAD7." (PMID 30876419, 2019). "The involvement of miR-106b-5p in modulating both cancer stem cells, via SMAD7, and the tumor microenvironment, through PTEN regulation in CAFs, highlights its broad impact on gastric cancer tumorigenesis." (PMID 41155295, 2025). "This elevated expression has been shown to alter the characteristics of cancer stem cells by directly targeting SMAD7 and consequently inhibiting the TGF-β signaling pathway in CD44-positive gastric cancer cells." (PMID 41155295, 2025). "The downregulation of circWNK1 leads to reduced SMAD family member 7 (SMAD7) expression and subsequent activation of the TGF-β pathway, promoting gastric cancer cell proliferation, migration, invasion, and EMT." (PMID 39512697, 2024). "MiR-106a from gastric cancer-derived exosomes can promote the apoptosis and MMT of PMCs by inhibiting the expression of SMAD7." (PMID 35740521, 2022). "Gastric cancer exosome-derived miR-21-5p induces MMT in PMCs and promotes tumor peritoneal dissemination by targeting SMAD7." (PMID 35740521, 2022).
gastric cancer (continued). "Additionally, miR-21-5p could inhibit TGFBR2 expression in the TGF-β signaling pathway, thereby suppressing myofibroblast differentiation, in contrast to other reports, in which miR-21-5p promoted gastric cancer and kidney fibrosis by upregulating Smad7 in the TGF-β signaling pathway." (PMID 34344478, 2021). "In gastric cancer, ASPP2 inhibited ubiquitin-dependent degradation of Smad7 by interacting with ITCH, leading to the suppression of TGF-β1-Smad2/3 signaling, which reduced migration and invasion of gastric cancer cells both in vitro and in vivo." (PMID 32420372, 2020). "By immunohistochemistry, it was demonstrated that 98 out of 304 patients (32.2%) who had undergone gastrectomy expressed Smad7 in gastric cancer tissues whereas no expression was detected in normal tissues." (PMID 24317436, 2013). "LncRNA MBNL2-AS1, which forms a competing endogenous RNA network with miR-424-5p and SMAD7, downregulated the TGF-β/EMT pathway, thereby inhibiting the invasion ability of gastric cancer (GC) cells." (PMID 37892233, 2023). "SMAD7, HIF-1α gene and HIF-1α protein may be jointly involved in tumor development and prognosis (act as oncogenic factors), while SEC13, GHRL, and lncRNA GHRLOS may act as tumor suppressor factors and thus could be considered as novel therapeutic targets for gastric cancer." (PMID 35449150, 2022).
diabetic nephropathy (23 papers, 2013 to 2025). "Although it has been reported that deletion of Smad7 enhances renal inflammation and fibrosis in obstructive nephropathy and diabetic nephropathy, role of Smad7 in ANG II-mediated hypertensive nephropathy, a major cause of end-stage kidney disease, remains unexplored." (PMID 23301086, 2013). "Interestingly, our previous study indicated that the activation of TGF-β1/Smad3 could be attributed to the loss of Smad7 signaling in diabetic nephropathy." (PMID 34775979, 2021). "As part of the TGF-β1 pathway, SMAD proteins, particularly SMAD2, SMAD3, SMAD4, and SMAD7, are crucial in diabetic nephropathy." (PMID 38972889, 2024). "The protective effect of Smad7 in diabetic kidney injury makes its overexpression a promising therapeutic target for diabetic nephropathy." (PMID 36428551, 2022). "Overactivation of TGF-β1/Smad3 signaling is accompanied by the degradation of Smad7, contributing to the activation of NF-κB signaling in diabetic nephropathy." (PMID 34775979, 2021). "Mechanistically, BHD inhibited the activation of TGF-β1/Smad3 and NF-κB signaling in diabetic nephropathy while suppressing Arkadia expression and restoring renal Smad7." (PMID 34775979, 2021). "Under fibrosis conditions, Smad7 is reduced while Smad3 is highly activated as seen in diabetic nephropathy, hypertensive nephropathy, and aristolochic acid-induced nephropathy." (PMID 32258028, 2020). "Animal experiments found that miR-21 expression affected the TGF-β1-induced renal tubular epithelial-to-mesenchymal transition in diabetic nephropathy by regulating Smad7." (PMID 26968995, 2016). "miR-21 overexpression enhances the TGF-β1-induced epithelial-to-mesenchymal transition by targeting Smad7 and aggravates renal damage in diabetic nephropathy." (PMID 26968995, 2016). "In our study, we found that administration of MG132 in diabetic nephropathy rats led to a decrease in body weight and Smad7 protein expression, while we did not observed the significant changes in the mRNA expression of Smad7." (PMID 24511554, 2014). "The UPP participated in the activation of the TGF-β pathway and induced the progress of diabetic nephropathy by ubiquitin degradation of Smad7." (PMID 24511554, 2014). "We have also shown that MG132 has a therapeutic effect on early diabetic nephropathy by blocking ubiquitin degradation of Smad7 and thus inhibiting activation of the TGF-β pathway." (PMID 24511554, 2014). "Most importantly, the discovery that deletion of Smad7 increases renal fibrogenesis in diabetic nephropathy, obstructive nephropathy, and hypertensive nephropathy further defines the functional role of Smad7, suggesting Smad7 as a therapeutic agent for the treatment of CKD." (PMID 36835428, 2023). "In addition, Smad7 is also a negative regulator of NF-κB signaling in both obstructive and diabetic nephropathy." (PMID 26807792, 2016). "Most importantly, the functional role of Smad7 is further defined by the findings that deletion of Smad7 accelerates renal fibrogenesis in obstructive nephropathy, diabetic nephropathy as well as hypertensive nephropathy, suggesting Smad7 as a therapeutic agent for treatment of CKD." (PMID 25852569, 2015). "Smad7 is an inhibitory Smad and plays a protective role in obstructive and diabetic kidney disease." (PMID 23301086, 2013). "Therefore, we speculate that BHD may protect against diabetic nephropathy probably by suppressing the Arkadia-dependent ubiquitin degradation of renal Smad7 and TGF-β/Smad3 signaling pathways." (PMID 34775979, 2021). "Thus, protection of Smad7 from degradation may be a key mechanism by which TSF inhibited diabetic kidney disease." (PMID 26807792, 2016). "This study aimed to investigate the effects of empagliflozin (SGLT2i) on cell viability, oxidative stress and TGF-β1 levels, collagen synthesis, as well as pSTAT3, pGSK3β, GSK3β, SMAD7, and pAKT expression in an LLC-PK1 model of diabetic nephropathy." (PMID 36428551, 2022).
diabetic nephropathy (continued). "After diabetic nephropathy mice were treated with BHD (2 g/kg), the expressions of p-Smad3, Arkadia, p-p65 were significantly down-regulated whereas the expression of Smad7 was upregulated." (PMID 34775979, 2021). "In contrast, an inhibitory Smad, Smad7, represses TGF-β/Smad3 and NF-κB signaling pathway by interacting with TGF-β receptors and functions as an antagonist of these molecules in diabetic nephropathy." (PMID 34775979, 2021). "In this study, we discovered that Smurf2, a member of the UPP family, increased in the diabetic nephropathy group, concomitantly with increased expression of TGF-β and FN, followed by decreased expression of Smad7." (PMID 24511554, 2014). "Moreover, treatment with empagliflozin augmented the expression of SMAD7, possibly leading to the downregulation of TGF-β1, one of the key mediators of inflammation and fibrosis in diabetic nephropathy." (PMID 36428551, 2022). "Notably, Smad7 is a key protein to suppress the activation of TGF‐β/Smad3 and NF-κB signaling pathways in diabetic nephropathy." (PMID 34775979, 2021). "Strikingly, the protein levels of TGF-β1, phosphor-Smad2, Smad4, and Smad7 were reversed after 8-weeks treatment with ergosterol, indicating that ergosterol can inhibit the renal TGF-β1/Smad2 signaling pathway in STZ-induced diabetic nephropathy mice." (PMID 30823598, 2019). "The possibility that MG132 is able to inhibit activation of the TGF-β signaling pathway through blocking ubiquitin degradation of Smad7 in diabetic nephropathy has not been studied." (PMID 24511554, 2014). "Therefore, a novel mechanism in diabetic nephropathy may be the activation of the UPP, which increases ubiquitin degradation of Smad7, which is a inhibiting factor in the TGF-β/SMAD signaling pathway." (PMID 24511554, 2014). "However, whether ubiquitin degradation of Smad7, which regulates the TGF-β signaling pathway, is involved in the development of diabetic nephropathy by the UPP is unknown." (PMID 24511554, 2014). "Thus, we tested the hypothesis that the anti-fibrotic and anti-inflammatory effects of BHD might be attributed to blocking the Smad3 phosphorylation and Arkadia, subsequently increasing renal Smad7 and inhibiting NF-κB signaling in the STZ-induced diabetic nephropathy mice." (PMID 34775979, 2021).